ENSG00000268083 (novel protein)
Gene: Protein-coding gene on chromosome 19 (38,817,471 to 38,840,178, reverse strand). Ensembl gene ENSG00000268083.
Genetic constraint (gnomAD): Loss-of-function variants: 9 observed, 38.5 expected, observed/expected ratio (o/e) 0.23, 90% interval 0.14 to 0.41. Missense variants: 304 observed, 436.82 expected, observed/expected ratio (o/e) 0.7, 90% interval 0.63 to 0.76. Synonymous variants: 172 observed, 159.44 expected, observed/expected ratio (o/e) 1.08, 90% interval 0.95 to 1.22.